AURKA (aurora kinase A)
Diseases named in the same sentence as AURKA in open-access papers (continued):
Sharing a sentence is not in itself a finding about the gene and the disease.
cancer (continued). "Furthermore, our findings revealed that READ, OV, and BRCA showed mainly heterozygous amplifications, whereas the frequency of heterozygous deletions was significantly higher in TGCT than in other cancers when analyzing the CNV situation of AURKA." (PMID 40718709, 2025). "In conclusion, a novel molecular signature panel including the AURKA, CEP55, DTL, and TTK genes could improve early cancer detection and diagnostic accuracy, and it may contribute to the treatment outcomes of PAN-gastrointestinal cancer patients." (PMID 40723362, 2025). "Furthermore, the dysregulation of AurkA and TPX2, adds further diagnostic value, as these proteins are frequently overexpressed in various cancers and are linked to tumor progression and therapeutic resistance." (PMID 39833908, 2025). "A clear pattern of AURKA alterations was observed in different cancer types." (PMID 40718709, 2025). "Indeed, several genes—such as BMYB, FOXM1, polo-like kinase 1 (PLK1), Aurora kinase A (AURKA), and CCNB1—regulated and suppressed by the DREAM complex are overexpressed in various cancers and are associated with a poor cancer prognosis." (PMID 39796178, 2025). "AURKA inhibitors impair mitotic spindle assembly, restrict cell cycle progression, and suppress AURKA activity, thereby inhibiting the proliferation, migration, and invasion of cancer cells." (PMID 40949156, 2025). "Additionally, existing evidence suggests that AURKA promotes PI3K/AKT activities across different cancer types." (PMID 40702875, 2025). "Furthermore, the expression levels of AURKA in different cancers showed discrepant correlations with 28 immune cell types." (PMID 40718709, 2025). "The AURKA-specific inhibitor alisertib, currently under clinical evaluation for various cancer types, suppress YAP1 Ser397 phosphorylation and restores cetuximab sensitivity both in vitro and in PDX models, further emphasising the significance of this event in primary resistance to cetuximab." (PMID 38467828, 2024). "Developing such effective combination therapies may thus unlock the full potential of AURKA as a critical drug target in cancer treatment." (PMID 39334449, 2024). "AURKA-mediated phosphorylation of NuMa inhibits apoptosis and promotes proliferation, suggesting that it might also serve as a cancer target of AURKA." (PMID 39334449, 2024). "A few of these mitotic targets could also serve as cancer targets either due to their overexpression and/or mislocalization along with AURKA in specific cancers." (PMID 39334449, 2024). "Our findings may potentially be consistent with the idea that APA positively contributes to shaping AURKA protein expression in certain cancers." (PMID 39527514, 2024). "It was found that OSU-2S may down-regulate the expression of S1PR1 and AURKA, which may prevent the growth of cancer cells." (PMID 38794152, 2024). "Additionally, certain microRNAs (miRNAs) control AURKA expression in cancers where its overexpression is a driving factor or a marker of poor prognosis." (PMID 39527514, 2024). "Recent studies on AURKA's oncogenic role have laid the foundations for developing novel anti‐cancer therapies targeting this kinase, which may be more effective than conventional chemotherapeutic regimens." (PMID 38590119, 2024). "In addition, we demonstrate that KRASG12C inhibitors decreased Aurora kinase A (AURKA) levels in cancer cells, and inhibition of AURKA using siRNA or inhibitors led to increased expression levels of GLI-1 and KRAS even in the absence of KRAS inhibitor." (PMID 38225225, 2024). "Mitotic defects in many human cancers are primarily due to abnormal expression of AURKA." (PMID 38612711, 2024). "We therefore add a new facet to the complex oncogenic expression program of the AURKA cancer gene, highlighting molecular mechanisms that could represent actionable targets of both DNA- and RNA-based therapeutics." (PMID 39527514, 2024).
cancer (continued). "Furthermore, NSD2 depletion potently inhibits cancer cells and renders them sensitive to growth inhibition by AURKA inhibitor alisertib." (PMID 39334449, 2024). "Indeed, the frequent occurrence of supernumerary centrosomes in cancer samples with high AurkA levels was reported." (PMID 39195284, 2024). "AURKA is also overexpressed in many cancers due to increased protein stability." (PMID 39334449, 2024). "Ectopic expression of AURKA also blocked ARS-1620–induced KRAS promoter activity in cancer cells." (PMID 38225225, 2024). "Based on our findings, we hypothesise that AURKA protein expression in cancer could result from dynamic post-transcriptional regulation by hsa-let-7a and APA, in combination or independently." (PMID 39527514, 2024). "Our data support the idea that hsa-let-7a tunes the expression of AURKA in some cancers." (PMID 39527514, 2024). "Therefore, mechanisms governing AURKA translation or degradation play a greater role in cancers with lower AURKA mRNA-protein correlation." (PMID 39527514, 2024). "In vivo studies have also suggested that AURKA is a plausible cancer therapeutic target." (PMID 39199578, 2024). "On these bases, the AurkA/TPX2 complex is emerging as a potential therapeutic target in cancer." (PMID 39195284, 2024). "We focused on a protein called Aurora kinase A (AURKA), which our prior study suggested may play a role in modulating resistance to the common cancer drug cisplatin." (PMID 39199578, 2024). "Meanwhile, AURKA was reported to act as an oncogene in a variety of cancers." (PMID 38287009, 2024). "Likewise, AURKA, and its oncogenic substrates are often independently reported to be concomitantly increased in many cancers." (PMID 39334449, 2024). "Blocking AURKA also increased markers that help the immune system recognize cancer." (PMID 39199578, 2024). "Before performing a pan-cancer analysis of AURKA expression, we first explored whether the inclusion or exclusion of unusual samples affected fold change estimates between cancer and normal tissues." (PMID 39527514, 2024). "Consequently, we found that AURKA inhibition had the capacity to effectively restore cetuximab sensitivity and concurrently suppress the cancer stem cell phenotype." (PMID 38467828, 2024). "We hypothesise that mechanisms influencing the ability of hsa-let-7a to target AURKA mRNA could limit the coupling between hsa-let-7a abundance and AURKA expression measurable in our pan-cancer analysis." (PMID 39527514, 2024). "Furthermore, the ‘protein vs SLR’ correlation was analysed in light of the cancer-dependent changes in AURKA SLR." (PMID 39527514, 2024). "We suggest that the interplay between APA and hsa-let-7a targeting of AURKA mRNA may influence AURKA expression in some cancers." (PMID 39527514, 2024). "Therefore, we argue that AURKA mRNA and protein expression are often discordant in cancer as a result of dynamic post-transcriptional regulation." (PMID 39527514, 2024). "Recent investigations into the role of AURKA inhibitors in the DNA damage response pathway and DNA repair have identified additional mechanisms by which AURKA inhibitors may be a promising cancer therapy." (PMID 38869684, 2024). "Since aberrant AURKA protein expression in cancer may derive from alterations in post-transcriptional events, this was further investigated in light of the reported role of hsa-let-7a miRNA in controlling AURKA expression." (PMID 39527514, 2024). "Interestingly, anti-cancer drugs targeting AURKA (e.g. Alisertib) are recently considered as potential therapeutic options." (PMID 38622359, 2024). "Correlation and clustering analyses of AURKA mRNA and protein expression, and expression of AURKA-targeting hsa-let-7a miRNA, unveiled that hsa-let-7a is likely involved to varying extents in controlling AURKA expression in cancers." (PMID 39527514, 2024). "Thus, AURKA cleavage provides a potential key biomarker for the efficacy of clinical cancer chemotherapy." (PMID 38994036, 2024).
cancer (continued). "Metformin enhanced immune cell-mediated killing of cancer cells in vitro, consistent with our observation that Alisertib or genetic loss of function led NK cells effectively targeting GBM cells due to decreased levels of PD-L1 resulting from blocking AURKA." (PMID 38995006, 2024). "Moreover, the AURKAD132 mutation attenuates the sensitivity of cells to Taxol compared to AURKAWT in vitro and in vivo, suggesting that the Taxol exerts anti-cancer effects by inducing Asp132-cleavage of AURKA." (PMID 38994036, 2024). "For instance, restoring the expression of tumor-suppressive miRNAs or suppressing oncogenic lncRNAs can attenuate AURKA expression, thereby inhibiting cancer cell proliferation, migration, and invasion as well as reducing the risk of resistance to standard anti-tumor agents." (PMID 39598228, 2024). "CCNA2, TTK, TOP2A, AURKA, AURKB and BUB1B are also closely associated with cancer." (PMID 39537209, 2024). "AURKA influences the activities of numerous transcription factors for cancer progression." (PMID 39334449, 2024). "AURKA also plays a role in resistance to apoptosis, a key challenge in cancer treatment." (PMID 39598228, 2024). "One source of variability in the correlation between hsa-let-7a and AURKA expression in different cancers could arise from differences in AURKA mRNA processing that would determine sensitivity to hsa-let-7a targeting." (PMID 39527514, 2024). "Additionally, we sought to understand the role of post-transcriptional regulation in AURKA expression in cancer." (PMID 39527514, 2024). "We first explored AURKA mRNA expression levels across cancers." (PMID 39527514, 2024). "AURKA inhibition may induce immune checkpoint expression in cancer cells and alter the composition or intrinsic cellular characteristics of cancer, immune, or stromal cells." (PMID 39199578, 2024). "Understanding the role of AURKA in cancer may improve liver tumour management and treatment, offering hope for better outcomes for patients in the future." (PMID 38590119, 2024). "AURKA exerts its cancer-inducing effects through the Wnt and MAPK signaling pathways." (PMID 36874006, 2023). "Notably, an aberrant expression or amplification of the AURKA gene (that codes Aurora A kinase) is common in various cancers, including AML." (PMID 36831387, 2023). "Therefore, development of specific AURKA inhibitors is thought to bear potential for cancer therapies." (PMID 37174007, 2023). "In our study, the lysosomal degradation of AURKA was discovered for the first time and it may also provide a new explanation for the molecular mechanism of high expression of AURKA in cancers." (PMID 37773181, 2023). "AURKA has recently garnered attention for its atypical expression in various human tumors, suggesting its potential as a vital biomarker for diagnosing and predicting the prognosis of diverse cancers." (PMID 37965456, 2023). "The finding that AURKA has a mitochondrial localization and that it increases mitochondrial ATP production when overexpressed provided an additional piece of evidence linking cancer biology, the cell cycle and mitochondrial metabolism." (PMID 37386025, 2023). "CD532, an AURKA kinase-independent confirmation-specific inhibitor, disrupts the AURKA-MYCN complex and drives the proteasomal degradation of MYCN in MYCN-driven cancers, suggesting a strategy to overcome AURKA kinase-independent oncogenic activity by disrupting protein-protein interactions." (PMID 37415951, 2023). "Overexpression of AURKA can inhibit apoptosis in human cancer." (PMID 36768482, 2023). "Indeed, our RNA-Seq results also echo those of a previous study that proposed the use of aurora kinase (AURKA) inhibitors for MLL4-mutant cancer." (PMID 37252797, 2023). "Aurora Kinase A (AURKA) also has tumorigenesis properties in different cancer types." (PMID 36900109, 2023).
cancer (continued). "We also identified the hotspot with the highest number of exclusively non‐cancer‐related pathogenic mutations that corresponds to R371 of the AURKA structure and has not been discussed previously." (PMID 37572333, 2023). "Nevertheless, it remains unclear whether METTL16 mediated m6A modification of lncRNAs can regulate AURKA activation in cancer progression." (PMID 37773181, 2023). "As a target for cancer therapy, some small molecules targeting AURKA have been discovered." (PMID 37773181, 2023). "Our results demonstrated significant associations between AURKA expression and TMB, MSI, and TIDE across a broad spectrum of cancers, suggesting that AURKA expression could potentially affect the effectiveness of immunotherapy." (PMID 37965456, 2023). "However, in specific cancers such as THYM, READ, COAD, OV, STAD, and LAML, our results indicated that higher AURKA expression was associated with improved prognosis." (PMID 37965456, 2023). "Several studies have indicated that AURKA plays an oncogenic role in cancer." (PMID 37965456, 2023). "In this regard, AURKA overexpression has been associated with the upregulation of stem cell markers such as SOX2 and NANOG, imposing participation in the maintenance of the self-renewal capacity of cancer stem cells (CSCs)." (PMID 36839989, 2023). "In HCC, AURKA promotes cancer metastasis and cancer stem cell properties." (PMID 37773181, 2023). "AURKA is highly expressed in tumor tissues and is a potential target for cancer therapy." (PMID 38053725, 2023). "Numerous studies have shown inhibition of protein degradation could contribute to the elevated levels of AURKA expression in cancer tissues, but the current reports on the AURKA degradation pathway focus on the Ubiquitin-proteosomal degradation pathway." (PMID 37773181, 2023). "AURKA, an oncogene from the serine/threonine kinase family, is responsible for activating the process of cell division through mitosis regulation and promoting tumorigenesis and metastasis in different cancer types, and this property qualifies AURKA as a potential target in cancer treatment." (PMID 36980449, 2023). "Last, our data suggest that ATP5F1A and ATP5F1B could be promising targets in AURKA-overexpressing cancers." (PMID 37386025, 2023). "Together, these results indicate an important function of TPX2 in regulation of AurkA interphase localization and suggest that it may play a role, independent of its activating function, in nuclear enrichment of the kinase in cancer." (PMID 36797043, 2023). "Several AURKA inhibitors are currently being studied in clinical trials in MM or other cancers." (PMID 37333985, 2023). "Interestingly, a well-known oncoprotein AURKA, which has been demonstrated to promote metastasis of cancer cells through activating EMT in several cancer types was identified by mass spectrometry as a TIALD binding candidate proteins." (PMID 37773181, 2023). "Aurora kinase A and B are frequently overexpressed in cancer cells compared with normal cells." (PMID 35745617, 2022). "Pathological overexpression of AURKA is correlated with shorter survival of cancer patients." (PMID 35664691, 2022). "In addition, we investigated the relationship between AURKA and immune cells in the pan-cancer microenvironment." (PMID 36685952, 2022). "Indeed, AURKA is found overexpressed in different cancers, typically as a result of gene amplification or enhanced transcription." (PMID 36067794, 2022). "It has been studied whether AURKA expression correlates with immune infiltration in ACC or other types of cancer." (PMID 36685952, 2022).
cancer (continued). "In these, activity of AURKA IRES element was found to be positively correlated with its protein levels, suggesting that a switch from cap- to IRES-dependent translation contributes to overexpression of AURKA at the level of translation, probably marking an early event during cancer progression." (PMID 36067794, 2022). "Furthermore, the MAP of mitosis bio-function predicted it as inhibited because of the downregulation of NUSAP1 and AURKA that directly modified this critical process in cancer development." (PMID 36478748, 2022). "The seven DEGs (AURKA, BUB1, CDC6, MAD2L1, NDC80, ZWINT, and TIMELESS) coexpressed only in the LC&OC coexpression network have been associated with the acquisition of the hallmarks of cancer." (PMID 36101460, 2022). "Furthermore, a review study has indicated that AURKA can become a target for cancer therapy and found that most tumor types show significantly higher AURKA expression than normal tissue in the TCGA database." (PMID 36050939, 2022). "Thus, a strategy of simultaneously targeting the kinase‐dependent and kinase‐independent functions of AURKA to induce mitotic catastrophe and impair cancer stemness is proposed to be a more effective therapeutic approach." (PMID 35652200, 2022). "Gene amplification, transcriptional activation, and the inhibition of protein degradation could contribute to increased AURKA expression in cancer tissues." (PMID 36291769, 2022). "Then, we looked at AURKA’s pan-cancer expression and its relationship to ACC pathological stage." (PMID 36685952, 2022). "Although the role of AURKA in promoting cancer cell survival and drug resistance has been established, its role in regulating prosurvival UPR in cancer cells remains unknown." (PMID 35326553, 2022). "In the present study, we designed and synthesized a novel quinazolin-4(3H)-one derivative, BIQO-19, with improved solubility and pharmacokinetic properties and which exhibits increased antiproliferative activity against cancer cells with aurora kinase A inhibition." (PMID 35745617, 2022). "In addition to its function as a cell cycle kinase, AURKA is considered as an inhibitor which prevents the chromatin assembly of functional replisomes, leading to sensitization of cancer cells to combination therapy." (PMID 35520289, 2022). "Importantly, YTHDC1-directed RBM4 splicing is governed by AURKA accumulated in the nucleus of cancer cells, therefore targeting AURKA with its nuclear translocation inhibitors effectively suppresses the oncogenic switch of RBM4 and tumor progression." (PMID 35361747, 2022). "Alisertib (MNL8237), an investigational inhibitor of Aurora kinase A developed by Takeda Inc., currently being tested in several adult cancer clinical trials, binds to the catalytic domain of Aurora kinase A and causes an allosteric change in the protein structure." (PMID 35053227, 2022). "In addition, AURKA promotes the proliferation and migration of cancer cells during mitotic interphase." (PMID 35699421, 2022). "Aurora kinase A is a major cell cycle regulatory protein which is overexpressed in cancer cells." (PMID 35745617, 2022). "The poor prognosis of cancer patients is related to the over-expression of AURKA." (PMID 36678556, 2022). "AURKA may have an indirect effect on cancer development and progression by modulating epigenetic status." (PMID 36685952, 2022). "Thus, the interaction and effective binding between the main OEO compounds and protein targets of PTEN and AURKA have been studied for their cancer treating potential via in silico molecular docking." (PMID 36678556, 2022). "The development of AURKA inhibitors has become a major challenge in cancer treatment." (PMID 36678556, 2022).